GLYCAM1 (glycosylation dependent cell adhesion molecule 1 (pseudogene))
Synonyms: GLYCAM1P
Gene: Transcribed unitary pseudogene on chromosome 12 (54,608,273 to 54,610,405, reverse strand). Ensembl gene ENSG00000257780.
Diseases named in the same sentence as GLYCAM1 in open-access papers:
GLYCAM1 is named in the same sentence as 7 diseases in open-access papers, as found by Europe PMC text mining. Sharing a sentence is not in itself a finding about the gene and the disease. The quoted sentences say what the papers report.
glaucoma (2 papers, 2017 to 2019). Increased pressure in the eyeball due to obstruction of the outflow of aqueous humor. "Supporting this, genetic knockout of Glycam1 on a DBA/2 J background increased glaucoma susceptibility (i.e. increased the risk that an eye would develop severe glaucoma) following radiation therapy." (PMID 30670050, 2019). "To investigate the role of Glycam1 in radiation-therapy in glaucoma, we developed the D2 mice with a null allele of Glycam1 (D2.Glycam1−/−)." (PMID 28446179, 2017). "Although genetic ablation of Glycam1 restored entry of monocyte-like cells into the ONH, glaucoma susceptibility was more modestly affected." (PMID 30670050, 2019). "Glycam1 is stably up-regulated following radiation treatment in glaucoma and monocyte entry into the optic nerve head is inhibited." (PMID 28446179, 2017). "In conclusion, we discover that transcription and protein expression of the proteoglycan ligand GlyCAM1 is increased in the long term following radiation therapy in D2 glaucoma." (PMID 28446179, 2017). "As there is increased vascular permeability in human glaucoma patients, it is possible that secreted soluble GlyCAM1 arrives at the inner retina through vascular leakage." (PMID 28446179, 2017). "The D2.Glycam1−/− mice and wild-type controls were γ-irradiated at 2–3 months of age and aged to the two key glaucoma time-points of 10.5 and 12 months of age." (PMID 28446179, 2017). "Glycam1 is constitutively up-regulated following radiation therapy and may protect from glaucoma by negatively modulating extravasation." (PMID 28446179, 2017). "Another possibility is that the cells entering irradiated Glycam1 deficient eyes do not have the same properties as those entering wild-type D2 eyes and that they are less capable of inducing glaucoma." (PMID 28446179, 2017). "Given the complexity of D2 glaucoma, as well as the complex, context-dependent regulation of extravasation, it is not surprising that Glycam1 does not solely mediate radiation-induced protection." (PMID 28446179, 2017). "Here, we generated a D2 substrain lacking Glycam1 to determine if GlyCAM1 is important for the radiation-induced neuroprotection and to determine if increased levels of GlyCAM1 impede extravasation in glaucoma." (PMID 28446179, 2017).
breast carcinoma (1 paper, 2015). "GLYCAM1 expression has not been evaluated in human breast cancer." (PMID 25633981, 2015).
colorectal cancer (1 paper, 2025). A primary or metastatic malignant neoplasm that affects the colon or rectum. "Notably, LncRNAs NEAT1, LOC152578, GLYCAM1, and SARS exhibited significantly reduced expression levels following aspirin treatment compared to untreated colorectal cancer cells." (PMID 40953835, 2025).
mastitis (1 paper, 2023). Inflammation of breast tissue during lactation or postpartum due to an obstructed duct or infection. "Although with no classification on PANTHER, the abundance of GLYCAM-1 significantly decreased during the course of lactation progression and in subclinical S. uberis mastitis milk compared to controls." (PMID 37889706, 2023).
tumor (4 papers, 2010 to 2022). "In keeping with the phenotypic loss of HEVs in tumor LNs, the expression levels of Glycam1, Chst4, Icam1, and Ccl21a were progressively reduced in HEC1 to HEC3, similar to the reduction of gene expression of PNAd producing glycan-generating enzymes." (PMID 34706240, 2021). "We found that, upon treatment with IM ± anti-VEGF, tumor endothelial cells expressed higher levels of Glycam1, which is expressed in mature HEVs." (PMID 36113478, 2022). "However, together with the lower expression levels of multiple glycosyl transferases, particularly Chst4, the overall lower level of Podxl, Glycam1, and Cd300lg in PNAd+ TEC may also contribute to the lower level of PNAd expression on the tumor vasculature." (PMID 36189308, 2022). "Thus, changes in Gast, Ccla3, Glycam1, Spp1, Serpina1a, Cela1, Cldn2, and Fabp2 are a result of GW501516 treatment and are not tumor specific." (PMID 21318167, 2010).
GLYCAM1 also shares sentences with these, for which no sentence is quoted: cancer (2 papers); Glucose intolerance (1).